MCL1 (MCL1 apoptosis regulator, BCL2 family member)
Diseases named in the same sentence as MCL1 in open-access papers (continued):
Sharing a sentence is not in itself a finding about the gene and the disease.
leukemia (continued). "Plasma cell leukemia cell line ARH77 had undetectable levels of MCL1 even prior to CDK-inhibition, suggesting an additional mechanism of cell death induction alongside MCL1 downregulation." (PMID 22558078, 2012). "More specifically, MCL-1 is related to almost all leukemias that show resistance to chemotherapy and bad prognosis." (PMID 21941553, 2012). "The kinase inhibitor BAY 43-9006 was shown to induce apoptosis in human leukaemia cells involving downregulation of Mcl-1 through the rapid and potent dephosphorylation of the eIF4E translation-initiation factor." (PMID 21750559, 2011). "Our study opens new applicative perspectives supported by the observation that specific targets for Mcl-1 in leukaemia are actively studied." (PMID 21750559, 2011). "The most prominent anti-apoptotic bcl-2 family members, including bcl-2 (B-cell CLL/lymphoma 2), bcl-XL (BCL2L1) and mcl-1 (myeloid cell leukemia 1; BCL2L3), were originally identified and found to be over-expressed in leukemia cells." (PMID 20105315, 2010). "Over-expression of Mcl-1 decreased sensitivity of leukemia cells to cytotoxic chemotherapeutic agents and specific down-regulation of Mcl-1 via RNA interference sensitized multidrug-resistant leukemia cells towards chemotherapy and induced apoptosis." (PMID 20663232, 2010). "More recently, it has been demonstrated that sorafenib induces apoptosis in human leukemia cells and other human tumour cell lines through down-regulation of the anti-apoptotic protein myeloid cell leukemia-1 (MCL-1), a Bcl-2 family member." (PMID 20003259, 2009). "In addition, leukemia cells from patients who had responded to VEN + AZA but relapsed during the course of treatment showed increased expression of BCL-XL or MCL1 compared to pre-treatment levels." (PMID 41615994, 2026). "On the other hand, the expression of BCL-XL and MCL1 in leukemia cells could be easily semi-quantified by immunostaining, with these results correlating with those obtained by qPCR." (PMID 41615994, 2026). "In the cells cultured in vitro, the synergistic use of HHT and BTZ enhanced the cytotoxicity of BTZ against K562 leukemia cells, reduced the expression of the anti-apoptotic proteins Bcl-2 and Mcl-1, while enhancing the expression of the pro-apoptotic protein Bax." (PMID 39949739, 2025). "Given the approval of TKI/Src inhibitors in the clinic, as well as the ongoing evaluation of MCL-1 antagonists in leukemia and multiple other malignancies, the Src/MCL-1 strategy may warrant attention in AML and potentially other neoplastic disorders." (PMID 39924517, 2025). "Additionally, Mcl-1-specific siRNA inhibition has been demonstrated to effectively induce apoptosis in leukemia cells and overcome chemoresistance." (PMID 40161373, 2025). "Furthermore, the activity of this degrader resulted in an increase in the expression of the MCL‐1 protein, which when used in conjunction with an MCL‐1 inhibitor induced synergistic leukemia cell death." (PMID 38845697, 2024). "We hypothesize that HHT reduces the Mcl-1 protein level and accelerates Ara-C-induced leukaemia cell apoptosis through multiple pathways." (PMID 38658865, 2024). "Our results imply that TK216 with venetoclax could be a potentially effective combination strategy for targeting Mcl-1-dependent leukemia cells." (PMID 37895265, 2023). "Their results showed that McL-1 and BAX could stimulate apoptosis in human leukemia by McL-1 down-regulation, BAX conformational change, and mitochondrial translocation, which resulted in cytochrome C release." (PMID 36926328, 2023). "This indicates the ability of TK216 to target Mcl-1 in these pediatric leukemia cells." (PMID 37895265, 2023).
leukemia (continued). "TPA has been shown to activate p-ERK and to increase the levels of Mcl-1 in leukemia cells." (PMID 36739272, 2023). "Notably, the down-regulation of MCL-1 by HMAs and the disruption of energy metabolism and targeting of leukemia stem cells by the Ven–HMA combination play an important role in promoting the observed synergy." (PMID 38203655, 2023). "CG-806 demonstrated much more pronounced anti-proliferative than pro-apoptotic effects, accompanied by only marginal inhibition of Bcl-2, Bcl-xL, and Mcl-1 as well in most of the tested leukemia cell lines, even upregulated the anti-apoptotic protein Mcl-1 in Ba/F3-FLT3-WT and ITD mutant cells." (PMID 36865133, 2023). "However, the treatment only marginally affected Bcl-2 and Bcl-xL levels in the leukemia cells, and even upregulated the anti-apoptotic protein Mcl-1 especially in Ba/F3-ITD mutant and Ba/F3-FLT3-WT cell lines." (PMID 36865133, 2023). "Aspirin could decrease the MCL1 expression level independently of the NF-κB and MAPKs pathways, promoting human leukemia cells apoptosis." (PMID 37488209, 2023). "Targeting MCL-1 may dysregulate the cellular metabolism and leukemia–stroma interactions and re-sensitize acute myeloid leukemia to BCL-2 inhibition." (PMID 36293442, 2022). "Additionally, onset of apoptosis of leukemia cells can further degrade Mcl-1 as this protein has two caspase cleavage sites." (PMID 35273915, 2022). "In summary, we have identified in the IS21 compound a pan ligand for Bcl-2, Bcl-xL and Mcl-1 anti-apoptotic members, which exhibits potent in vitro and in vivo efficacy against human leukemia and melanoma cancer models, offering the potential for further preclinical investigation." (PMID 35265218, 2022). "Preliminary indications that BH3 mimetics may modulate NK cell attack have been provided by a recent report indicating that the Mcl-1 inhibitor maritoclax may cooperate with NK cells to kill leukemia cells." (PMID 35013156, 2022). "The functional role of MCL1 in cancer stemness other than leukaemia yet has been less investigated." (PMID 35794816, 2022). "MCL1 is another antiapoptotic protein involved in leukemia cell survival." (PMID 35865470, 2022). "Similarly, the inhibitor of cyclin-dependent kinase 9 (CDK9) induced AML apoptosis by down-regulating the expression of MCL1 and demonstrated anti-leukemia and clinical activity in refractory and relapsed (R/R) AML." (PMID 35865470, 2022). "Interestingly, some venetoclax-resistant leukemias were sensitive to the MCL-1-selective antagonist S63845 and/or BCL-XL-selective A-1331852 suggesting functional mutual substitution." (PMID 35031695, 2022). "In addition, FLT3 inhibitors have been shown to cause anti-proliferative activity, in leukaemia cell lines with FLT3-ITD, through the downregulation of MCL-1 and BIRC5, the latter via the STAT3/5 pathway." (PMID 34638823, 2021). "In addition, a decrease in phosphorylation of RNAPII and expression of MCL-1 was observed in leukemia blasts of some patients treated with alvocidib who achieved a CR59." (PMID 34112754, 2021). "Furthermore, in the context of B cell lineage leukaemia’s, the heme-sensing pathway modulated apoptotic sensitivity by repressing MCL-1 and increased their responsiveness to BH3-mimetics." (PMID 35008835, 2021). "Together, these findings suggest that chidamide may induce venetoclax-resistant leukaemia suppression by downregulating MCL1, which could be further exploited in future clinical trials." (PMID 34956909, 2021).
leukemia (continued). "mTORC1 signaling in leukemia cells regulates other growth and survival factors besides cyclin D3 and MCL-1; for example, knockdown or inhibition of mTORC1 in human T-ALL cells reduces expression of the oncoprotein c-MYC while increasing expression of the pro-apoptotic protein PUMA." (PMID 34408976, 2021). "Moreover, it was found that MIM1 can selectively inhibit Mcl-1 protein and induce caspase 3/7 activation and cell death in Mcl-1-dependent leukemia cells." (PMID 31432325, 2020). "Moreover, it is demonstrated that patients with solid tumors and leukemia benefit from decreased Mcl-1 expression or reducing its stability." (PMID 31601252, 2019). "Our findings suggested that holotoxin A1 may be a useful candidate in developing treatments for human leukemias that feature overexpression of Bcl-xL and Mcl-1." (PMID 29642569, 2018). "Our results suggest that cladoloside C2 may be a useful candidate for the treatment of human leukemia overexpressing Mcl-1 and Bcl-xL." (PMID 29416631, 2018). "As expected, stromal cells increased MCL1 abundance in leukaemia cells." (PMID 29665227, 2018). "Our previous study reported that YM155 abolishes the expression of Mcl-1 in leukemia cells." (PMID 29340073, 2017). "While aspirin reportedly inhibits MCL-1 expression in leukemia cells and oral squamous carcinoma cells, the current study demonstrates that aspirin up-regulates MCL-1 expression in colon cancer cell line SW480, but down-regulates MCL-1 in aspirin sensitive RKO and HCT-116 cells." (PMID 26918349, 2016). "In addition, YM155 down-regulates survivin and Mcl-1 expression, leading to induction of caspase-8-dependent apoptosis in leukemia cells." (PMID 27528031, 2016). "In addition, degradation of Mcl-1 by cathepsin B plays a critical role on FTY720-induced leukemia apoptosis." (PMID 27528031, 2016). "Importantly, we have previously shown that wild-type Mcl-1 when transduced into leukemia cells confers resistance to the BH3 mimetics ABT-263 and ABT-199." (PMID 27738316, 2016). "Furthermore, increase of Mcl-1 protein stability is observed in this leukemia model, suggesting the Mcl-1 protein level directly contributes to the resistance of flavopiridol." (PMID 25596730, 2015). "Further research will focus on whether Mcl-1 and Bcl-2 could be directly target by miR-29 and miR-29b and how will they work in leukemia cells." (PMID 25006537, 2014). "Therefore, we analysed primary and secondary Fli-1 leukaemias and MigR1 controls for Bcl-2, Bcl-xL and Mcl-1 mRNA expression by Q-PCR." (PMID 23667468, 2013). "Sorafenib, developed as a BRAF inhibitor, reduces MCL1 translation leading to increased apoptosis in leukemia cells while Flavopiridol, a cyclin-dependent kinase inhibitor, suppresses MCL1 and has been used to treat patients with high-risk chronic lymphocytic leukemia (CLL)." (PMID 23762095, 2013). "High levels of MCL1 were found in solid human tumors and cell lines derived from human leukemia or lymphomas; furthermore, studies in vivo showed that knockdown of NOXA or co-expression of MCL1 and oncogene MYC can significantly accelerate the development of tumors such as lymphoma or leukemia." (PMID 22548841, 2012). "Similarly, suppression of Mcl-1 expression in some leukaemias and lymphomas potentiates vinblastin-induced apoptosis." (PMID 21750559, 2011). "Expression of the anti-apoptotic protein Mcl-1 is frequently elevated in various human tumors including leukemia, but the underlying mechanisms causing its elevation are not fully understood." (PMID 21608150, 2011). "Overexpression of mcl-1 can inhibit cell death by stabilizing the outer mitochondrial membrane potential, and several recent leukemia treatment strategies have attempted to target the expression of mcl-1 by either pharmacological inhibition or siRNA-mediated downregulation." (PMID 20105315, 2010). "Mcl-1 is a crucial regulator of cell death in leukemia cells." (PMID 20105315, 2010).
leukemia (continued). "Our investigations show that nelfinavir, despite its ability to induce death of leukemia cells, induces an upregulation of the cell-protective mcl-1 protein in human leukemia cells that might stabilize the mitochondria even under apoptotic conditions." (PMID 20105315, 2010). "Pro-survival protein Mcl-1 and pro-oncoprotein c-Myc are critical regulators that promote the survival of leukemia cells; HHT could affect the survival of leukemia cells by allowing the rapid loss of short-lived Mcl-1 and c-Myc to facilitate proapoptotic triggering." (PMID 30388805, 2018). "Particularly relevant in leukemia are the proapoptotic protein Bax, the antiapoptotic protein Bcl-xL, which prevents cytoplasmatic release of cytocrome c and, the antiapoptotic protein Mcl-1, which is able to bind to caspases in order to inhibit apoptosis signaling." (PMID 27557509, 2017). "The upregulation of anti-apoptotic proteins, such as BCL-2 and MCL-1, in response to JAK-STAT activation, can make leukemia cells more resistant to the pro-apoptotic effects of chemotherapeutic agents." (PMID 40486651, 2025). "The role of aza has been described in the literature as a synergistic inhibitor of the proteins MCL1 and BCL-xL, thereby increasing the dependence of leukemia cells on BCL2." (PMID 40973765, 2025). "MCL-1, a member of the BCL-2 family with anti-apoptotic functions, is a key contributor to chemoresistance in multiple cancers, including leukemia." (PMID 41294812, 2025). "Our study found that CTSD knockdown promoted apoptosis in leukemia cells by inducing the degradation of the anti-apoptosis proteins BCL2, BCL-XL, and MCL1." (PMID 40796615, 2025). "By enhancing the expression of anti-apoptotic proteins such as BCL-2 and MCL-1, JAK-STAT signaling can help leukemia cells resist the cytotoxic effects of chemotherapy." (PMID 40486651, 2025). "Mechanistic study revealed that STM2457 augmented venetoclax activity by downregulating MCL1 and MYC, thereby increasing apoptosis in leukemia cells induced by venetoclax." (PMID 40169588, 2025). "For instance, overexpression of BCL‐2, myeloid cell leukemia 1 (MCL‐1), and BCL‐XL has been observed in lymphomas and leukemias." (PMID 39619229, 2024). "It dose-dependently inhibited the phosphorylation of RNAP II CTD (Ser 2), and downregulated MCL-1 and MYC to induce apoptosis and arrest the cell cycle at the G0/G1 phase in leukemia cells." (PMID 37272701, 2023). "miR-145 and miR-181 promote apoptosis of leukemia stem cells through regulation of ABCE1 and MCL-1 respectively, and miR-424 inhibits BCR-ABL activity." (PMID 37476380, 2023). "Azacitidine inhibits the prosurvival proteins MCL1 and BCL-XL, thereby increasing the dependence of leukemia cells on BCL2, which is directly targeted by venetoclax." (PMID 37046645, 2023). "In the human leukemia xenograft animal model, PEITC induced tumor cell apoptosis and reduced tumor growth via downregulations of AKT, JNK, and Mcl-1." (PMID 35368876, 2022). "By downregulating MCL1 and inducing the expression of the pro-death proteins NOXA and PUMA, azacytidine inhibits synergistically the pro-survival proteins MCL1 and BCL-XL, increasing the dependence of leukemia cells on BCL-2." (PMID 36008542, 2022). "Secondly, HG3 cells are resistant to the treatment of drugs able to inhibit antiapoptotic Bcl-2 family members, such as ABT-737, due to the overexpression of Mcl-1, a downstream effector of activating AKT in CLL and other leukemia." (PMID 33477701, 2021). "To clarify the role of MCL1 in ABZ-induced apoptosis, we investigated the cytotoxicity of ABZ on human leukemia K562 cells." (PMID 32486166, 2020). "S63845 is a selective MCL1 inhibitor that can selectively bind to the BH3-binding groove of MCL1, thereby effectively killing MCL1-dependent tumor cells, including MM, leukemia, and lymphoma cells." (PMID 33292251, 2020).
leukemia (continued). "Human leukemia cell line RS4;11 which is dependent on BCL-2 for survival was more sensitive to Maritoclax treatment compared to HeLa cells which are dependent on MCL-1 for survival." (PMID 33214852, 2020). "Marinopyrrole A (maritoclax) has recently been identified as a naturally occurring compound with the ability to inhibit the BIM-MCL-1 interaction, induce proteolytic degradation of MCL-1, and potentiate apoptosis of leukemia cells." (PMID 31150457, 2019). "Thus, targeting both ABCB1 and MCL‐1 may help overcome drug resistance in human leukemia." (PMID 30891950, 2019). "In MLL-AF9 leukemia models overexpressing BCL-2 and MCL-1 it was provided evidence that the combination of BCL-2 and MCL-1 inhibitors resulted in a synergistic anti-leukemic effect, when used alone or in combination with standard anti-leukemic drugs." (PMID 30813354, 2019). "MCL1 and MYC were also shown to cooperate in mouse models of leukemia and non-small cell lung cancer (NSCLC), and co-expression of these two factors correlates with poor NSCLC patient survival." (PMID 30674894, 2019). "We found that a broad range of anti-leukaemic agents–notably MCL-1 inhibitors, DNA damaging agents and FLT3 inhibitors–sensitise leukaemia cells to BAD-BH3." (PMID 29298347, 2018). "Irrespective of the expression of anti-apoptotic BCL-2 family members, the re-programmed p185+ B-ALL cells in which endogenous MCL-1 was replaced by human BCL-2, BCL-XL, BCL-W, MCL-1, or BFL-1 all succumbed to a fatal leukemia with a similar kinetic." (PMID 26862853, 2016). "For examples, cathepsin B degrades Mcl-1 proteins, resulting in apoptosis of FTY720-treated leukemia cells, and YM155 also induced down-regulation of Mcl-1 expression via lysosome-dependent manner in human oral cancer cells." (PMID 27582546, 2016). "We then characterized a panel of ABT-199-resistantmyeloid leukemia cell lines derived through chronic exposure to ABT-199 and foundthat acquired drug resistance is indeed driven by the upregulation of MCL-1 andBCL-XL." (PMID 27283158, 2016). "UM-36 appears to have modest selectivity for MCL-1, with similar response in BFL-1-dependent leukemia, which correlates with the in vitro binding affinity of this class of MCL-1 inhibitor showing less selective inhibition of BFL-1." (PMID 26862853, 2016). "It has recently been shown that Mcl-1 is required for survival during BCR-ABL transformation and in established BCR-ABL(+) leukaemia." (PMID 26184865, 2015). "It is worthy of note that normal B-cells show significantly lower levels of transcription of MCL1 and XIAP compared to CLL cells perhaps providing a rationale for the preferential toxicity of CDKI-73 in leukemia cells." (PMID 24495868, 2014). "As shown in this study, dinaciclib has direct anti-leukemia cytotoxicity but effects are of short duration, suggesting that it needs to be combined with chemotherapy or other novel agents whose activity may be enhanced by dinaciclib-induced down-regulation of Mcl-1 in acute leukemias." (PMID 23949430, 2013). "Pharmacodynamic data demonstrated a rapid decrease in Mcl-1 protein levels and induction of PARP cleavage in patients’ peripheral blood leukemia cells upon dinaciclib treatment, but with quick recovery once dinaciclib level declines." (PMID 23949430, 2013). "Moreover, the up-regulation of genes involved in inhibition of apoptosis (e.g. MCL1) may promote the survival of leukemia cells with accumulated DNA damage and their expansion as suggested by an up-regulation of genes involved in cell cycle progression (AHR, AHR, TUBB2A, RAPGEF3, SERTAD1, FLT1)." (PMID 22848414, 2012).